SNHG31 (small nucleolar RNA host gene 31)
Gene: Long non-coding RNA gene on chromosome 2 (214,809,470 to 214,963,622, forward strand). Ensembl gene ENSG00000229267.
Diseases named in the same sentence as SNHG31 in open-access papers:
SNHG31 is named in the same sentence as 1 disease in open-access papers, as found by Europe PMC text mining. Sharing a sentence is not in itself a finding about the gene and the disease.
SNHG31 shares sentences with these, for which no sentence is quoted: prostate carcinoma (1 paper).